NDUFS8 (NADH:ubiquinone oxidoreductase core subunit S8)
Description:
Core subunit of the mitochondrial membrane respiratory chain NADH dehydrogenase (Complex I) which catalyzes electron transfer from NADH through the respiratory chain, using ubiquinone as an electron acceptor. Essential for the catalytic activity and assembly of complex I.
Synonyms: TYKY; CI-23k; CI23KD; MC1DN2
Tractability: Small molecule: an approved drug acts on it; a structure with a bound ligand is known. Antibody: UniProt places it where antibodies can reach, with medium confidence. PROTAC: ubiquitination databases record sites on it; its protein half-life has been measured.
Gene: Protein-coding gene on chromosome 11 (68,030,617 to 68,036,647, forward strand). Ensembl gene ENSG00000110717.
Subcellular location: Mitochondrion inner membrane
Subcellular location (Human Protein Atlas): Mitochondria
Pathways (Reactome):
Metabolism: Complex I biogenesis; Respiratory electron transport
Gene Ontology:
Molecular function: NADH dehydrogenase (ubiquinone) activity; NADH dehydrogenase activity; protein binding; 4 iron, 4 sulfur cluster binding; oxidoreductase activity, acting on NAD(P)H
Biological process: mitochondrial electron transport, NADH to ubiquinone; mitochondrial respiratory chain complex I assembly; aerobic respiration; proton motive force-driven mitochondrial ATP synthesis; proton transmembrane transport
Cellular component: mitochondrial inner membrane; mitochondrion; respiratory chain complex I; mitochondrial matrix; membrane
Genetic constraint (gnomAD): Loss-of-function variants: 13 observed, 26.67 expected, observed/expected ratio (o/e) 0.49, 90% interval 0.32 to 0.77. The upper end of that interval is the gene's LOEUF score, 0.77, which puts it in group 3 of 6, group 1 being the genes least tolerant of losing a copy. Missense variants: 257 observed, 311.42 expected, observed/expected ratio (o/e) 0.83, 90% interval 0.74 to 0.92. Synonymous variants: 119 observed, 123.54 expected, observed/expected ratio (o/e) 0.96, 90% interval 0.83 to 1.12.
Gene-disease validity (ClinGen):
ClinGen rates the evidence that NDUFS8 causes each of these diseases.
mitochondrial disease (autosomal recessive): Definitive.
Leigh syndrome (autosomal recessive): Moderate. A progressive neurological disease defined by specific neuropathological features associating brainstem and basal ganglia lesions.
Homologues: Orthologues: chimpanzee NDUFS8 (100% identical), macaque NDUFS8 (95% identical), guinea pig NDUFS8 (94% identical), pig NDUFS8 (94% identical), dog NDUFS8 (93% identical), mouse Ndufs8 (90% identical), rat Ndufs8 (90% identical), zebrafish ndufs8a (81% identical), tropical clawed frog ndufs8 (77% identical), Drosophila melanogaster ND-23 (73% identical), Caenorhabditis elegans ndus-8 (66% identical).
Diseases named in the same sentence as NDUFS8 in open-access papers:
NDUFS8 is named in the same sentence as 49 diseases in open-access papers, as found by Europe PMC text mining. Sharing a sentence is not in itself a finding about the gene and the disease. The quoted sentences say what the papers report.
Leigh syndrome (8 papers, 2018 to 2022). "Pathogenic variants of the NDUFS8 are relevant to infantile-onset and severe diseases, including Leigh syndrome, cancer, and diabetes mellitus." (PMID 36557887, 2022). "Pathogenic variants of NDUFS8 contribute to the onset of Leigh syndrome primarily by affecting the assembly of complex I, not only because of the misfolding of NDUFS8, but also owing to impaired interaction of other subunits and NDUFS8." (PMID 36557887, 2022). "Based on this, pathogenic variants of the NDUFS8 are relevant to infantile-onset and severe diseases, including Leigh syndrome, cancer, and diabetes mellitus." (PMID 36557887, 2022). "The first nuclear-encoded subunit mutations of complex I in a patient with Leigh syndrome are missense mutations in the NDUFS8, followed by several patients with different pathogenic variants." (PMID 36557887, 2022). "NADH dehydrogenase (ubiquinone) Fe-S protein 8 (NDUFS8) is a nuclear-encoded core subunit of human mitochondrial complex I. Defects in NDUFS8 are associated with Leigh syndrome and encephalomyopathy." (PMID 34204592, 2021). "Another Complex 1 protein, NDUFS8, previously had been implicated in a human disorder called Leigh Syndrome." (PMID 32357532, 2020). "A confusing aspect of Leigh Syndrome has been the variation in phenotype among patients carrying the identical mutant alleles of NDUFS8." (PMID 32357532, 2020). "Since Denis Leigh’s first description of Leigh syndrome in 1951, many pathogenic mutations causing Leigh syndrome have been revealed, mostly linked to pathways of energy generation, but only 14 pathogenic variants of NDUFS8 causing Leigh syndrome have been reported." (PMID 36557887, 2022). "Variants related to Complex I such as NDUFS8, NDUFS7, and NDUFA2 are found to be explanations for Leigh syndrome, a neurodegeneration showing degenerative foci in the central neural system." (PMID 36431159, 2022). "Besides Leigh syndrome, cancer, and diabetes mellitus, as a core subunit of complex I, NDUFS8 has a relation with neural and psychiatric diseases." (PMID 36557887, 2022). "Currently, there are only several studies on pathogenic variants of the NDUFS8 in Leigh syndrome, and a lack of literature on its precise mechanism in cancer and diabetes mellitus exists." (PMID 36557887, 2022). "NDUFS8‐related disorder was first described in an infant with Leigh syndrome (LS) and cardiomyopathy who died at 11 weeks of age." (PMID 36101822, 2022).
breast carcinoma (4 papers, 2024 to 2025). "Unique mutations in genes such as NDUFS2, MGST3, PRDX6, NDUFS8, and GSTP1 were found predominantly in breast cancer." (PMID 39594421, 2024). "Our analysis revealed that mutations in OSRE such as MGST3, GSTP1, NDUFS2, NDUFS8 and PRDX6 were particularly prevalent in breast cancer, and for the five genes the most prevalent genetic alteration was amplification." (PMID 39594421, 2024). "Thus, these analyses uncovered the possible association of the CI functionality—the NAD+‐regenerating capability accompanied by electron transfer by NDUFS1, NDUFS7, and NDUFS8—with cancer progression in patients with HR(+)/HER2(−) breast cancer." (PMID 39873399, 2025).
lung carcinoma (4 papers, 2016 to 2025). "The opposite prognostic effect of NDUFS1 and NDUFS8 reflects the oncojanus role of nDNA-encoded core subunits and the panel combining NDUFS1 and NDUFS8 expressions predicts lung cancer prognosis." (PMID 27516145, 2016). "NDUFS1 and NDUFS8 as the leading prognostic factors in 7 nDNA-encoded core subunits can be a useful panel for prognosis prediction and therapeutic decision in lung cancer patients." (PMID 27516145, 2016). "Taking together, the panel combining NDUFS1 and NDUFS8 expression could be used to predict the risk of poor prognosis more precisely by reflecting the metabolism status of lung cancer." (PMID 27516145, 2016). "For example, low NDUFS1 and high NDUFS8 expression levels in lung cancer were found to predict poor overall survival." (PMID 35831908, 2022). "The panel with NDUFS1 and NDUFS8 reflecting tumor metabolism status is a novel prognostic predictor for lung cancer." (PMID 27516145, 2016). "Elevated levels of NDUFS8 expression were observed in cancer cell populations from both LUAD and LUSC, indicating its relevance across different lung cancer subtypes." (PMID 40258810, 2025).
acute myeloid leukemia (3 papers, 2022 to 2023). Acute myeloid leukemia (AML) is a group of neoplasms arising from precursor cells committed to the myeloid cell-line differentiation. "Similarly, according to the survival analysis, the increased expression level of NDUFS8 was associated with poorer overall survival in patients with acute myeloid leukemia (AML)." (PMID 36557887, 2022). "As prognostic factors, patients with high expression of NDUFS8 in NSCLC or acute myeloid leukemia has poor overall survival." (PMID 37469574, 2023).
non-small cell lung carcinoma (3 papers, 2016 to 2025). A group of at least three distinct histological types of lung cancer, including non-small cell squamous cell carcinoma, adenocarcinoma, and large cell carcinoma. "Similarly, one study found that the NMGs NDUFS1 and NDUFS8 (encoding subunits of mitochondrial complex 1) had significant prognostic power in the patients with non-small cell lung cancer (NSCLC) by analyzed immunohistochemical staining and RNA expression data." (PMID 34760888, 2021). "The results revealed that low NDUFS1 expression and high NDUFS8 expression are correlated with poor prognosis and have leading prognostic roles in non-small cell lung cancer." (PMID 27516145, 2016).
Parkinson disease (3 papers, 2018 to 2022). A progressive degenerative disorder of the central nervous system characterized by loss of dopamine producing neurons in the substantia nigra and the presence of Lewy bodies in the substantia nigra and locus coeruleus. "This analysis revealed that the genes implicated in Parkinson’s disease (Atp5a1, Ndufa7, Ndufb2, Ndufs8, Park7, Cox7a2, Cox7c, Cox6b1, Cycs, Uchl1) were upregulated in thia-exposed mice (p-value = 4.2E-3)." (PMID 34295895, 2021). "Compared with middle-aged individuals, there were obvious upexpressions of NDUFS8 in the frontal cortex in those with Parkinson’s disease, but notable downexpressions in those with Parkinson’s disease with dementia." (PMID 36557887, 2022). "Next we interrogated the KEGG pathway and found the top up-regulated categories showed strong correlation with Alzheimer’s, Huntington’s and Parkinson’s diseases by enriching genes such as ATP5D, ATP5H, HSD17B10 and NDUFB11, NDUFA8, NDUFB7, NDUFS8." (PMID 29915338, 2018).
diabetes mellitus (2 papers, 2022). A metabolic disorder characterized by abnormally high blood sugar levels due to diminished production of insulin or insulin resistance/desensitization. "It has been found that a higher serum concentration of NDUFS8 was linked to higher insulin sensitivity among people with type 1 diabetes mellitus, which might reflect better mitochondrial function." (PMID 36557887, 2022). "Some trials have been made in patients with diabetes mellitus, in which they discovered the possible role of NDUFS8 change." (PMID 36557887, 2022). "There was a similar result that showed that NDUFS8 expression was upregulation in high-fat diet-induced obesity-dependent diabetes mouse models, especially in the liver tissue." (PMID 36557887, 2022). "According to recent studies, different types of diabetes mellitus show diverse relevance to NDUFS8, from reflecting mitochondrial function to promoting diabetes formation." (PMID 36557887, 2022). "Nevertheless, there is no published literature on pathogenic variants of NDUFS8 in diabetes but pathogenic mutations exist in other mitochondrial subunits in diabetes." (PMID 36557887, 2022). "In addition, with the development of the link between other subunits of complex I and cancer or diabetes mellitus, the results have gradually emerged, while the relation between NDUFS8 and these diseases is poorly studied." (PMID 36557887, 2022). "When it comes to pathogenic variants of the NDUFS8 and diabetes mellitus, there is no study available, which implies that we can use WGS and WES to explore if the mutations exist." (PMID 36557887, 2022). "Multivariate linear regression confirms a significant association between insulin sensitivity and a higher concentration of NDUFS8 in serum (beta = 0.54, p = 0.003), independent of age, duration of diabetes, and smoking." (PMID 36135178, 2022). "Owing to its vital structure of tetranuclear FeS clusters (N6a and N6b) and function of electron transfer, NDUFS8 plays a crucial role in different diseases and clinical processes, although there is no exact mechanism for cancer and diabetes mellitus." (PMID 36557887, 2022).
hepatocellular carcinoma (2 papers, 2022 to 2025). A malignant tumor that arises from hepatocytes. "First, we analyzed the expression of NDUFS8 in hepatocellular carcinoma (HCC) using data from The Cancer Genome Atlas (TCGA) project." (PMID 40914145, 2025). "The elevated NDUFS8 could also be found in hepatocellular carcinoma (HCC), which was associated with the dedifferentiation of HCC." (PMID 36557887, 2022). "To investigate the potential function of NDUFS8 in hepatocellular carcinoma (HCC) cells, we silenced NDUFS8 using two non-overlapping shRNA sequences (NDUFS8-sh1 and NDUFS8-sh2)." (PMID 40914145, 2025).
Insulin resistance (2 papers, 2022). Increased resistance towards insulin, that is, diminished effectiveness of insulin in reducing blood glucose levels. "Additionally, NDUFS8 exhibited increased interaction with insulin receptor substrate 1, which was linked to inflammation-mediated insulin resistance in T2DM patients." (PMID 36557887, 2022).
type 1 diabetes (2 papers, 2022 to 2025). "Additionally, elevated serum levels of NDUFS8 have been correlated with improved insulin sensitivity in patients with type 1 diabetes [PMID: 36,135,178], and NDUFS8 has also been identified as a candidate gene for Alzheimer’s disease." (PMID 40914145, 2025).
type 2 diabetes (2 papers, 2022 to 2025). "Among these, mitochondrial-associated proteins such as the NADH:ubiquinone oxidoreductase subunit proteins NDUFS5, NDUFA10 and NDUFS8 were downregulated in type 2 diabetes." (PMID 40295335, 2025).
adenoma (1 paper, 2022). A neoplasm arising from the epithelium. "NDUFS8 was significantly differentially expressed between benign and malignant adrenocortical tumors (p < 0.05) with an overall accuracy of 87–91%, suggesting that NDUFS8 was a good diagnostic marker for distinguishing ACC from adenoma." (PMID 36557887, 2022).
chronic gastritis (1 paper, 2020). Inflammation of the stomach that is chronic in nature. "The down-regulation of NDUFS8 (NADH: Ubiquinone Oxidoreductase Core Subunit S8), MT2A (Metallothionein 2A), HDAC7 = Histone Deacetylase 7, and PDK1 (Pyruvate dehydrogenase kinase 1) in chronic gastritis and intestinal metaplasia, respectively, was also confirmed." (PMID 31897247, 2020).
cognitive deficits (1 paper, 2026). "To establish the causal role of NDUFS8 deficiency in the basal forebrain in cognitive impairment, we first used small interfering RNAs (si) to suppress expression of NDUFS8 in primary cultured BFNs." (PMID 41355955, 2026). "Collectively, all these results strongly suggest that gain-of-function of NDUFS8 exerts a profoundly beneficial effects on cognitive impairment in CCH rats, along with corresponding improvements in mitochondrial function." (PMID 41355955, 2026). "Crucially, targeted restoration of NDUFS8 expression in the basal forebrain effectively rescues CCH-induced cognitive deficits." (PMID 41355955, 2026).
hyperhomocysteinemia (1 paper, 2022). A serious metabolic condition caused by mutations in the MTHFR gene, medications, or nutritional deficiency. "Paraoxonase1 deficiency and hyperhomocysteinemia changed the expression of mouse kidney proteins related to renal diseases, and downregulation of NDUFS8 could account for the involvement of hyperhomocysteinemia and reduced Paraoxonase1 in kidney disease through energy metabolism." (PMID 36557887, 2022).
hypertrophic cardiomyopathy (1 paper, 2020). A condition in which the myocardium is hypertrophied without an obvious cause. "Ndufs8, like Ndufs4, is a peripheral membrane protein which can contribute to hypertrophic cardiomyopathy." (PMID 33287280, 2020).
latent infections (1 paper, 2019). "In normal to latent infections, we identified eight genes, of which three genes (FZD2, NDUFS8, NLRC4) were up-regulated, and another five genes (CCL4, IL1B, IL1A, TNF, AREG) were down-regulated." (PMID 31749827, 2019).
leukodystrophy (1 paper, 2022). Leukodystrophies are a group of rare, progressive, metabolic, genetic diseases that affect the brain, spinal cord and often the peripheral nerves. "Our report expands the neuroimaging phenotype of NDUFS8‐related disorder to include progressive leukodystrophy with increasing brainstem and cerebellar involvement, with relative sparing of the basal ganglia." (PMID 36101822, 2022).
Macrocephaly (1 paper, 2014). Occipitofrontal (head) circumference greater than 97th centile compared to appropriate, age matched, sex-matched normal standards. "Participant 178 is a 14-month-old male with macrocephaly and two ROHs on chromosomes 2 and 11 involving the HSPD1, PACS1, NDUFV1, and NDUFS8 genes that may play a role in psychomotor delay, hypotonia, and atypical development." (PMID 25400949, 2014).
pancreatic cancer (1 paper, 2022). "In this work, we observed that knockout of the NADH dehydrogenase complex subunit genes NDUFB10, NDUFC2, NDUFC2-KCTD14, NDUFS8 led to a decrease in the sensitivity of MIA PaCa-2 pancreatic cancer cells to oxaliplatin." (PMID 35209078, 2022).
Pleural effusion (1 paper, 2025). The presence of an excessive amount of fluid in the pleural cavity. "Additionally, NDUFS8 was upregulated in epithelial cells within LUAD pleural effusion samples, further emphasizing its role in LUAD progression." (PMID 40258810, 2025).
proliferative diabetic retinopathy (1 paper, 2024). Advanced retinopathy due to diabetes mellitus characterized by the formation of new vessels in the retina. "Lastly, we observed an increase in NDUFS8 expression in retinal proliferative membrane tissues obtained from human patients with proliferative diabetic retinopathy." (PMID 38594244, 2024).
prostate carcinoma (1 paper, 2025). A carcinoma that arises from epithelial cells of the prostate gland. "Importantly, compared to castration-sensitive prostate cancer (CSPC) tissues, CRPC tissues exhibited significantly higher mRNA levels of SNRPA, NDUFS8, and NDUFS9, as well as increased ATP contents and mtDNA levels." (PMID 41354732, 2025).
prostate tumors (1 paper, 2025). "Immunohistochemical analysis further confirmed lower expression levels of representative proteins such as Ndufa13 and Ndufs8 in prostate tumors derived from Lonp1KI mice and Pten−/−; Lonp1KI mice when compared to those from the control group." (PMID 39971909, 2025).
psoriasis (1 paper, 2021). An autoimmune condition characterized by red, well-delineated plaques with silvery scales that are usually on the extensor surfaces and scalp. "In blood heat syndrome, a common syndrome of psoriasis, we found that a large number of oxidative phosphorylation pathway-related genes, such as NDUFS8, NDUFA6, and UQCRC1, showed syndrome-specific expression abnormalities." (PMID 35126107, 2021).
rhabdomyolysis (1 paper, 2022). Necrosis or disintegration of skeletal muscle often followed by myoglobinuria. "Although there are many diseases related to NDUFS8, the unknown significance of some pathogenic variants in NDUFS8 remained, such as the variants of exertional rhabdomyolysis in NDUFS8." (PMID 36557887, 2022).
sarcopenia (1 paper, 2023). Progressive decline in muscle mass due to aging which results in decreased functional capacity of muscles. "We isolated MBs from the muscles of young (2.5 months old) and aged (24 months old) WT mice to investigate the impact of sarcopenia on Ndufs8 expression in MBs." (PMID 37857600, 2023).
steatosis (1 paper, 2018). Increased lipid within the cytoplasm of cells. "Thus, in line with our results, decreased expression of the mitochondrial biogenesis transcription factors PGC1α and NRF1, and decreased expression of respiratory Complex I and V subunits NDUFS8 and ATP5G1 in the HepG2 cell model of steatosis have been reported." (PMID 29949946, 2018).